RBM5-AS1 (RBM5 antisense RNA 1)
Synonyms: LUST
Gene: Long non-coding RNA gene on chromosome 3 (50,099,603 to 50,100,988, reverse strand). Ensembl gene ENSG00000281691.
Diseases named in the same sentence as RBM5-AS1 in open-access papers:
RBM5-AS1 is named in the same sentence as 6 diseases in open-access papers, as found by Europe PMC text mining. Sharing a sentence is not in itself a finding about the gene and the disease.
RBM5-AS1 shares sentences with these, for which no sentence is quoted: depression (2 papers); arousals (1); HIV-1 infection (1); rheumatoid arthritis (1); systemic lupus erythematosus (1); tumor (1).